C10orf90 (chromosome 10 open reading frame 90)
Synonyms: FLJ32938; bA422P15.2; FATS
Tractability: PROTAC: ubiquitination databases record sites on it.
Gene: Protein-coding gene on chromosome 10 (126,424,997 to 126,798,708, reverse strand). Ensembl gene ENSG00000154493.
Gene Ontology:
Molecular function: ubiquitin protein ligase activity
Biological process: protein polyubiquitination; protein stabilization; protein ubiquitination; regulation of centriole replication
Cellular component: actin cytoskeleton; centrosome; cytoplasm; cytosol; centriole
Genetic constraint (gnomAD): Loss-of-function variants: 49 observed, 60.25 expected, observed/expected ratio (o/e) 0.81, 90% interval 0.65 to 1.03. The upper end of that interval is the gene's LOEUF score, 1.03, which puts it in group 4 of 6, group 1 being the genes least tolerant of losing a copy. Missense variants: 887 observed, 895.35 expected, observed/expected ratio (o/e) 0.99, 90% interval 0.94 to 1.05. Synonymous variants: 353 observed, 349.05 expected, observed/expected ratio (o/e) 1.01, 90% interval 0.93 to 1.1.
Homologues: Orthologues: macaque C9H10orf90 (94% identical), chimpanzee C10H10orf90 (86% identical), pig C10orf90 (71% identical), dog C10orf90 (64% identical), guinea pig C10orf90 (61% identical), mouse D7Ertd443e (58% identical), rat C1h10orf90 (56% identical), tropical clawed frog c7h10orf90 (22% identical). Paralogues in human: ALMS1 (23% identical), CEP295 (15% identical), CEP295NL (2% identical).
Diseases named in the same sentence as C10orf90 in open-access papers:
C10orf90 is named in the same sentence as 29 diseases in open-access papers, as found by Europe PMC text mining. Sharing a sentence is not in itself a finding about the gene and the disease. The quoted sentences say what the papers report.
breast carcinoma (8 papers, 2010 to 2024). "Furthermore, C10orf90 variants have been reported to be associated with the risk of various cancers, including breast cancer and conjunctival melanomas." (PMID 37588090, 2023). "It has been demonstrated that the expression of C10orf90 is downregulated in breast cancer samples and that cancer patients exhibit significant genetic variations in the C10orf90 gene, which are associated with susceptibility to breast cancer." (PMID 39408824, 2024). "The expression of C10orf90 gene is downregulated or silenced in many cancers, and it is related to non-small cell lung cancer, breast cancer, and others." (PMID 37588090, 2023). "The C10orf90 gene has been identified as having a significant inhibitory impact on the advancement of various tumors, including non-small cell lung cancer, conjunctival melanoma, and breast cancer." (PMID 39408824, 2024). "Clinical data confirm a significant reduction in disease-free survival and a similar trend in 5-year overall survival for C10orf90-negative breast cancer patients compared to C10orf90-positive patients." (PMID 39408824, 2024).
Colon Cancer (2 papers, 2010 to 2024). "Notably, in COAD, C10orf90 inhibits the proliferation and migration of colon cancer cells, induces apoptosis, and is linked to the advancement of colon cancer." (PMID 39408824, 2024). "Cell experiments demonstrate that C10orf90 suppresses the proliferation and migration of colon cancer cells while promoting apoptosis." (PMID 39408824, 2024). "In addition, we have preliminarily demonstrated that at the cellular level, high expression of C10orf90 could inhibit the proliferation and migration of colon cancer cells and induce apoptosis." (PMID 39408824, 2024). "Finally, the bioinformatics results were used to confirm that overexpression of the C10orf90 gene could inhibit the proliferation and migration of colon cancer cells, induce apoptosis, and play a positive anticancer role at the cellular level." (PMID 39408824, 2024).
colorectal cancer (2 papers, 2023 to 2024). A primary or metastatic malignant neoplasm that affects the colon or rectum. "The based information of selected SNPs in C10orf90 and the association with the risk of colorectal cancer in the allele model." (PMID 37588090, 2023). "Selected variants in C10orf90 associated with the risk of colorectal cancer." (PMID 37588090, 2023). "Specifically, in COAD, the C10orf90 gene is involved in several immune-related processes and can inhibit the proliferation and migration of colorectal cancer cells." (PMID 39408824, 2024).
conjunctival melanoma (2 papers, 2023 to 2024). "Studies have shown that in conjunctival melanoma, the deletion of the tumor suppressor gene C10orf90 is related to the significantly reduced metastasis-free survival of tumor patients." (PMID 37588090, 2023). "In addition, the deletion of C10orf90 can lead to mutations in NRAS (an oncogene) and BRAF (a proto-oncogene), the latter two of which can confer greater therapeutic resistance and increased invasiveness to conjunctival melanoma." (PMID 39408824, 2024).
pterygium (2 papers, 2021 to 2024). A wedge-shaped fibrovascular lesion arising from the bulbar conjunctiva and extending to the cornea. "Among the top DEGs were four genes encoding tumor suppressors that were downregulated in pterygium: C10orf90, RARRES1, DMBT1 and SCGB3A1; C10orf90 and RARRES1 were also downregulated in pinguecula." (PMID 34769520, 2021). "RARRES1 and SCGB3A1 were identified in previous pterygium gene profiling studies, while C10orf90 and DMBT1 are new." (PMID 34769520, 2021).
alcoholism (1 paper, 2024). "The KEGG analysis revealed that C10orf90 was associated with systemic lupus erythematosus, alcoholism, neutrophil extracellular trap formation, taste transduction, olfactory transduction, and neuroactive ligand-receptor interaction." (PMID 39408824, 2024).
colon adenocarcinoma (1 paper, 2024). "Previous research findings indicate that C10orf90 expression is significantly downregulated in colon adenocarcinoma compared to normal and adjacent tissues, which has been demonstrated to have a high diagnostic value." (PMID 39408824, 2024).
Hearing impairment (1 paper, 2021). A decreased magnitude of the sensory perception of sound. "Five of the variants that have rare genotypes with large effects are at loci that have not been reported for any type of hearing impairment: FBF1, FSCN2, C10orf90, SH2D4B, and TBX2." (PMID 34108613, 2021).
kidney cancer (1 paper, 2024). Primary or metastatic malignant neoplasm involving the kidney. "Moreover, the protein expression level of C10orf90 is decreased in liver cancer and kidney cancer tissues, and the expression varies among different subtypes of BRCA, SKCM, and TGCT." (PMID 39408824, 2024). "Similarly, analysis of HPA data indicates that the levels of the C10orf90 protein expression are decreased in liver and kidney cancer tissues compared to normal tissues." (PMID 39408824, 2024).
lymph node metastasis (1 paper, 2023). "In the study, stratified analysis by clinical features (stage, lymph node metastasis, and cancer style) for the association between C10orf90 variants and the risk of CRC was investigated." (PMID 37588090, 2023).
cancer (14 papers, 2010 to 2025). A tumor composed of atypical neoplastic, often pleomorphic cells that invade other tissues. "Our results indicate that C10orf90 has prognostic and diagnostic value in various cancers." (PMID 39408824, 2024). "In the TIMER database, we identified a correlation between C10orf90 expression and six types of tumor-infiltrating immune cells, including NK cells, monocytes, macrophages, endothelial cells, myeloid dendritic cells, and cancer-associated fibroblasts." (PMID 39408824, 2024). "Our findings indicate that C10orf90 demonstrates favorable diagnostic value across multiple cancers, as evidenced by an area under the curve (AUC) exceeding 0.5 in 24 cancer types and even surpassing 0.7 in 13 types of cancers." (PMID 39408824, 2024). "In summary, C10orf90 plays a role in the onset and progression of various cancers and could potentially serve as an effective diagnostic and prognostic marker for cancer patients." (PMID 39408824, 2024). "We analyzed the levels of C10orf90 expression across various cancer immune and molecular subtypes using the TISIDB database." (PMID 39408824, 2024). "Pan-cancer analysis results reveal that the expression levels of C10orf90 vary across different tumors and hold significant value in the clinical diagnosis and prognosis of patients with various tumors." (PMID 39408824, 2024). "In some cancers, the expression level of C10orf90 is correlated with CNV, DNA methylation, immune subtypes, immune cell infiltration, and drug sensitivity in the tumors." (PMID 39408824, 2024). "In these cancers, C10orf90 was positively correlated with the majority of methylation-related genes." (PMID 39408824, 2024). "The results demonstrated that C10orf90 exhibited correlations with m1A, m5C, and m6A-related genes in most cancers, particularly in BLCA, HNSC, KICH, LUSC, OV, THCA, and UVM." (PMID 39408824, 2024). "This explains the abnormal expression of C10orf90 in various tumors, which is closely related to the rapid proliferation of cancer." (PMID 39408824, 2024). "The findings of the pan-cancer study suggest that the C10orf90 protein is present in a variety of bodily organs and tissues, including the testis, brain, breast, forearm, colon, kidney, liver, and pancreas." (PMID 39408824, 2024). "Subsequently, the correlation between C10orf90 expression in pan-cancer and the degree of tumor-infiltrating immune cells was validated using the TIMER database." (PMID 39408824, 2024). "Its human counterpart, C10orf90, a functionally uncharacterized gene, is mapped to a CFS FRA10F at 10q26, spanning a LOH region associated with cancers." (PMID 23109895, 2012). "In addition, there is a significant correlation between high levels of C10orf90 expression and unfavorable prognostic outcomes in several types of cancer, including KIRC, LGG, OV, STAD, and UVM." (PMID 39408824, 2024). "Therefore, we investigated the gene function of C10orf90 in various tumors using multiple pan-cancer datasets." (PMID 39408824, 2024). "Among these cancers, KIRC exhibited the most pronounced association with C10orf90." (PMID 39408824, 2024). "Therefore, we conducted a pan-cancer analysis of the C10orf90 gene using multiple databases and bioinformatics tools." (PMID 39408824, 2024). "Consequently, the objective of this study is to analyze the pan-cancer functionality of the C10orf90 gene in order to enhance the understanding of its biological role in different malignant tumors." (PMID 39408824, 2024). "Furthermore, we examined the transcript levels of C10orf90 mRNA in different subtypes of various cancers, uncovering diverse expression patterns of C10orf90 mRNA in different subtypes of BRCA, SKCM, and TGCT." (PMID 39408824, 2024). "The clinical data sourced from TCGA were utilized to perform univariate Cox regression analysis, investigating the association between C10orf90 expression and overall survival (OS), disease-specific survival (DSS), and progression-free interval (PFI) across diverse cancer types." (PMID 39408824, 2024).
cancer (continued). "C10orf90 is associated with a variety of cancers, but the correlation between C10orf90 and CRC is not yet known." (PMID 37588090, 2023). "Additionally, the promoter of C10orf90 exhibited hypomethylation in 20 cancer types." (PMID 39408824, 2024). "The data indicate that among immunostimulators, C10orf90 is positively correlated with immunostimulators in tumors such as COAD, PAAD, and UVM, while it is negatively correlated in cancers such as SKCM, TGCT, and THCA." (PMID 39408824, 2024). "Consistent with the literature, the results of the present study showed fusion of the FGFR2 gene with nine different partners, namely, TACC2, BICC1, BTBD16, WAC, HFM1, HOOK1, INPP5F, C10orf90, and WDR11, in five different types of cancer." (PMID 35342406, 2022). "We observed a correlation between C10orf90 and CNV in 6 cancer types." (PMID 39408824, 2024). "In addition, C10orf90 is positively correlated with immunoinhibitors in tumors such as COAD, PAAD, and UVM, while it is negatively correlated in cancers such as SKCM, TGCT, and THCA." (PMID 39408824, 2024). "Despite utilizing multiple databases and bioinformatics tools to analyze the role of the C10orf90 gene in various cancers, there is still a lack of extensive clinical samples and experimental data for validation." (PMID 39408824, 2024). "Previous studies have predominantly concentrated on exploring the genetic involvement of C10orf90 in individual cancer types, without conducting a comprehensive pan-cancer analysis of C10orf90, especially in COAD." (PMID 39408824, 2024). "Conversely, C10orf90 demonstrated a similar pattern of correlation with immunoinhibitors in tumors such as COAD, PAAD, and UVM, with a negative correlation observed in SKCM, TGCT, and THCA cancers." (PMID 39408824, 2024). "The results demonstrated that among the immunostimulators, C10orf90 exhibited a positive correlation with the immunostimulators in tumors such as COAD, PAAD, and UVM, and a negative correlation with SKCM, TGCT, and THCA cancers." (PMID 39408824, 2024). "However, for other cancers, including immune subtypes such as BLCA, CHOL, ESCA, LGG, LIHC, SKCM, and USC, as well as molecular subtypes like GBM, the expression of C10orf90 is not statistically significant." (PMID 39408824, 2024).
tumor (14 papers, 2010 to 2024). "The C10orf90 gene is characterized by a distinctive fragile site structure, which is susceptible to disruption during the rapid proliferation of tumor cells." (PMID 39408824, 2024). "Given the presence of immune cell infiltration in the tumor microenvironment, which is closely linked to the efficacy of immunotherapy, we initially investigated the correlation between C10orf90 and genes identified as immune checkpoint genes." (PMID 39408824, 2024). "As a tumor suppressor associated with fragile sites, C10orf90 is involved in DNA damage-induced carcinogenesis." (PMID 37588090, 2023). "The C10orf90 gene has been shown to promote the phenotypic shift from M2-like macrophages to anti-tumor M1-like macrophages." (PMID 39408824, 2024). "Most interesting were the 4 genes that function as tumor suppressors: C10orf90, RARRES1, DMBT1, and SCGB3A1." (PMID 34769520, 2021). "The cluster of associated variants overlaps intronic and 5’ regions of C10orf90 (or FATS, HGNC: 26563), a tumor suppressor gene." (PMID 33661925, 2021). "This highlights the importance of studying C10orf90 expression as part of tumor immunotherapy." (PMID 39408824, 2024). "C10orf90, a tumor suppressor, can inhibit the occurrence and development of tumors." (PMID 39408824, 2024). "The tumor suppressor genes affected by the 10q deletions in BRAF-mutated tumors include those located at 10q11-23 (RASSF4, C10orf99, and PTEN) and at 10q26 (DMBT1, C10orf90)." (PMID 37761808, 2023). "However, in patients with GBM and SKCM, the expression of C10orf90 mRNA was positively correlated with CNV expression, while the correlation was not significant in other tumor types." (PMID 39408824, 2024).
C10orf90 also shares sentences with these, for which no sentence is quoted: lung carcinoma (3 papers); breast tumor (2); non-small cell lung carcinoma (2); ovarian carcinoma (2); cervical cancer (1); gastric cancer (1); glioma (1); head and neck squamous cell carcinoma (1); liver cancer (1); lymphoma (1); melanoma (1); osteosarcoma (1); ovarian tumors (1); pancreatic cancer (1); pinguecula (1); systemic lupus erythematosus (1); Tinnitus (1).